NAT1 (N-acetyltransferase 1)
Diseases named in the same sentence as NAT1 in open-access papers (continued):
Sharing a sentence is not in itself a finding about the gene and the disease.
cancer (continued). "In this study our objective was to further investigate the role of NAT1 in pathways commonly dysregulated in cancer." (PMID 35046826, 2021). "We and others have previously reported that depletion of NAT1 in cancer cell lines often leads to a reduction in growth potential under specific conditions." (PMID 32555504, 2020). "Inhibition of NAT1 activity in cancer cells either by siRNA-mediated silencing, small molecular inhibitors or gene deletion with CRISPR/Cas 9 editing results in changes in cell survival and invasion." (PMID 31910058, 2020). "Here, we report the effects of NAT1 in cancer cell invasion by addressing its role in adherence, migration, and invasion in vitro." (PMID 31910058, 2020). "Previous investigations have demonstrated that NAT1 has an effect on biological features of human cancer, such as cell proliferation, invasion, metastasis, and drug resistance and is a biomarker of cancer prognosis." (PMID 32793479, 2020). "NAT1 expression varies inter-individually and has been shown to be elevated in several cancers including estrogen receptor-positive (ER+) breast cancers." (PMID 32555504, 2020). "Recently, many studies have been concentrated on the role of NAT1 in the tumorigenesis and progression of human cancers." (PMID 32793479, 2020). "In summary, the current study has established a novel role for NAT1 in cancer cells, especially during nutrient-deprived conditions." (PMID 29518119, 2018). "A second set consisted of an additional 15 cancer-related genes (Nf1, Mki67, Mllt4, Fgfr2, Ctnnb1, Fat1, Clp1, Fat4, Arid1a, Nat1, Nat2, Setd2, Impg1, Nbas and Npat)." (PMID 29925311, 2018). "The expression of NAT1 in over 40 cancer microarray studies was recently reviewed and a number of cancers showed significant differences between normal and malignant tissues." (PMID 29969986, 2018). "The role of human NAT1 in cancer is not well understood, but the current understanding of NAT1’s potential importance in cancer is expanding." (PMID 28359264, 2017). "The present study adds to the developing and complex narrative of NAT1 in cancer, by providing the first animal model data that show an association between NAT1 activity levels and tumorigenesis independent of carcinogen metabolism." (PMID 28359264, 2017). "Unpublished data from our laboratory suggests that human NAT1 knockout cancer cell lines have elevated AcCoA concentrations compared to their wildtype counterparts." (PMID 28359264, 2017). "This study assessed the role of NAT1 polymorphisms on susceptibility to OSCC, the interaction of NATs with alcohol and meat consumption on OSCC risk, and the role of NATs on cancer susceptibility in African populations." (PMID 25886288, 2015). "The human genome contains two polymorphic NAT genes, (HUMAN)NAT1 and (HUMAN)NAT2, which play important pharmacogenetic roles in cancer susceptibility and have the potential to contribute to personalised medicine." (PMID 25432241, 2014). "The role of NAT1 and NAT2 acetylator polymorphisms in cancer risk from aromatic and heterocyclic amine carcinogens will become clearer with more precise determinations of both exposures and genotypes." (PMID 24151610, 2013). "Cam and coworkers showed that NAT1 mRNA expression decreased by 57% in cancer cells following growth arrest induced by contact inhibition." (PMID 21347396, 2011). "This is an interesting observation that led us to examine the phenotypic changes induced in cancer cells with altered expression of the NAT1 protein." (PMID 21347396, 2011). "Arylamine N-acetyltransferase 1 (ARY1) is a key enzyme in various cancers, including GBC." (PMID 40470116, 2025). "Among these, NAT1, BIRC3, EZH2, MAD2L1, ATP2A3, HMGA1, and BST2 are known cancer-associated genes." (PMID 41255601, 2025). "Several studies have shown that NAT1 is upregulated in cancer cells." (PMID 35153780, 2022).
cancer (continued). "Several studies have shown that NAT1 is upregulated in cancer cells, the results of the present study show that the acetylation status of NAT1 is an important factor that might have a relevant role in the progression of cancer." (PMID 35153780, 2022). "The results of the present study show that the acetylation status of NAT1 is an important factor that might have a relevant role in the progression of cancer." (PMID 35153780, 2022). "It has been reported that NAT1 is a novel drug target in cancer development." (PMID 32793479, 2020). "NAT1 expression also varies from human cancer types and tumor stages." (PMID 32793479, 2020). "NAT1 plays different roles in different human cancer types or different tumor stages." (PMID 32793479, 2020). "While the NAT2 isoenzyme has a major role in the metabolism of xenobiotics, including therapeutic drugs and carcinogens, growing evidence supports an additional role for NAT1 in physiological processes (notably folate and methionine metabolism) and cancer cell biology." (PMID 31068377, 2019). "Although it appears that NAT1 KO can influence the cell morphology and cell-cell interactions in cancer cell lines, further investigation is needed into whether or not NAT1 depletion ultimately alters metastatic potential in vivo." (PMID 31531019, 2019). "Thus, the relationship of AcCoA levels to alterations in cancer growth properties observed in NAT1 KO cells requires further investigation." (PMID 31531019, 2019). "Based on this, we can speculate that depletion of NAT1 could in turn lead to increased levels of AcCoA, which occurred in two of the three cancer cell lines investigated in our study." (PMID 31531019, 2019). "NAT1, ex-pressed in many human cancer cell lines, is an enzyme that N-acetylates arylamine carcinogens and drugs (initial metabo-lism) in A375.S2 cells as well as other cancer cell lines." (PMID 30895270, 2018). "Recent findings in vitro suggest that NAT1 activity level also may influence cancer cell proliferation and survival." (PMID 28359264, 2017). "However given ubiquitous expression of NAT1, the findings here are likely to be observed in other cancer sites such as lung, colon, urinary bladder, and prostate." (PMID 28359264, 2017). "In particular, (HUMAN)NAT1 is up-regulated in several cancer types, thereby leading to cancer cell growth and resistance to chemotherapy, and has emerged as a viable candidate for drug development, which should lead to small molecule inhibitors for preclinical and clinical evaluation." (PMID 27242013, 2016). "This makes NAT1 an attractive drug target in cancer therapeutics." (PMID 25627111, 2015). "None of these studies have associated the effects of NAT1 on cancer cell survival with the acetylation activity of the enzyme." (PMID 25627111, 2015). "The NAT1 and NAT2 polymorphic variants may influence the metabolism of arylamine carcinogens and modulate the individual susceptibility to cancer upon exposure to environmental risk factors." (PMID 25886288, 2015). "The identification of (HUMAN)NAT1 as a potential therapeutic target in cancer means that understanding the molecular details of this series of enzymes in humans and potential animal models is important for their potential exploitation in both diagnostics and therapy." (PMID 25432241, 2014). "Tumors were considered positive for NAT1 if > 75% of the cancer cells showed cytoplasmic staining." (PMID 22333393, 2012). "It shows that NAT1 may function beyond a Phase II xenobiotic metabolizing enzyme and raises the possibility that it is a potential therapeutic target in cancer." (PMID 21347396, 2011). "Recent bioinformatics studies have correlated NAT1 expression with various cancer subtypes." (PMID 21347396, 2011). "We hypothesized that NAT1 and/or NAT2 polymorphisms contribute to the increased cancer evident in IBD." (PMID 17537267, 2007). "This difference in NAT1 expression in cancer may be attributed to organ-specific differences." (PMID 32793479, 2020).
cancer (continued). "Furthermore, previous studies have revealed that NAT1 is a prognostic biomarker of cancer." (PMID 32793479, 2020). "In addition to its function as a xenobiotic metabolizing enzyme, the results presented here suggest that NAT1 may also act as a regulator of cancer cell growth and survival." (PMID 25627111, 2015). "In addition, there have been some reports that NAT1 has an important role in cancer cell biology." (PMID 25528056, 2014). "The linkage disequilibrium between the genes of NAT1 and NAT2 has been observed in HNC and other cancers." (PMID 34684132, 2021). "Others have shown deletion of the NAT1 gene in MDA-MB-231, HT-29 and HeLa cancer cell lines leads to increased collagen adherence, decreased invasion, and morphological changes but no changes to migration ability in all three cell-lines." (PMID 35046826, 2021). "Five core ADME genes coding for phase II drug metabolism enzymes showed significant associations of their intratumoral expression levels with OS rates in cancers, including GSTP1, NAT1, UGT1A1, UGT2B15, UGT2B7." (PMID 33202946, 2020). "We have already pointed out the link between NAT1 and EMT status in a previous gene expression profiling-based study and its potential role, particularly as a drug target in cancer development." (PMID 30610490, 2019). "In addition, it suggests that NAT1 may be a novel drug target for cancer therapeutics." (PMID 21347396, 2011). "For example, although NAT1 is highly expressed in BRCA compared to other cancer types, our model did not select it." (PMID 35267493, 2022). "Taken together, these results show that both cancer cell lines switch between apoptosis and necroptosis when NAT1 expression is absent." (PMID 35918499, 2022). "As CBD is suspected to exert anti-cancer effects, it may be prudent in future work to investigate if CBD supplementation alters NAT1 activity." (PMID 34336977, 2021). "We firstly found that XBP1 and NAT1 have a negative association in expression and clinicopathological significance in GBC, which is never reported in other human cancers." (PMID 32793479, 2020). "Despite this functional validation of the NAT1 KO, the effects on endogenous levels of AcCoA and cancer cell growth were not completely consistent across different cell lines." (PMID 31531019, 2019). "Although most studies have focused on the role of NAT1 and NAT2 genetic polymorphisms in COAD risk, the potential role played by their aberrant expression in COAD has largely been ignored and whether NAT1 and NAT2 expression influences cancer patient survival remains unknown." (PMID 34322151, 2021).
tumor (43 papers, 2006 to 2025). "The limited scope of current studies has made it difficult to draw any conclusion on whether a causal relationship exists between tumour NAT1 expression and drug sensitivity." (PMID 35918499, 2022). "Moreover, NAT1 was positively correlated with ER and PR expression, negatively correlated with BC tumor grade and size, and associated with longer survival in BC patients treated with tamoxifen and in patients with lymph node metastasis." (PMID 35163157, 2022). "Finally, the association between survival and NAT1 sub-populations, tumor size, age at diagnosis, and treatment was investigated using univariate and multivariate Cox proportional hazard regression models." (PMID 29969986, 2018). "A cluster enriched for genes associated with the luminal/ER+ tumor subtypes (N-acetyltransferase 1, estrogen receptor 1, putative G-protein-coupled receptor, trefoil factor 3, GATA binding protein 3, and X-box binding protein 1) was also present in this gene set." (PMID 17150101, 2006). "The results also imply that the loss of NAT1 in patient tumours may contribute to drug resistance." (PMID 35918499, 2022). "However, high tumour NAT1 expression is associated with better patient outcomes and survival." (PMID 35918499, 2022). "The high expression of NAT1 is positively correlated with TMErisk scores, indicating its role in tumor progression." (PMID 40104502, 2025). "Strikingly, NAT1 overexpression was correlated with increased tumor cell apoptosis, as determined by TUNEL and Annexin V/PI staining." (PMID 39610918, 2024). "NAT1 can exert anti-tumor activity by inhibiting the phosphorylation of pi3k/Akt/mTOR signaling pathway." (PMID 37626132, 2023). "In those patients treated with chemotherapy, there was a strong positive relationship between tumour NAT1 expression and survival over the first 5 years post-treatment." (PMID 35918499, 2022). "Later, NAT1 and NAT2 polymorphisms were associated with an increased risk of LSCC, and a correlation between NAT1*10/*11 genotype frequency and tumor location was also observed." (PMID 35406495, 2022). "Using TargetscanHuman v7.1 software to determine putative target genes for miR-6744-5p, NAT1 enzyme was selected for further analysis due to the similarities between our in vitro findings and existing studies on NAT1 enzyme expression and breast cancer." (PMID 32296579, 2020). "In this study, we firstly identified that NAT1 was down-expressed in GBC tissues compared with that in adjacent non-tumor tissues, which is similar to previous reports." (PMID 32793479, 2020). "Conversely, NAT1 was down-expressed in GBC tissues in comparison with corresponding non-tumor tissues." (PMID 32793479, 2020). "NAT1 expression was scored as positive in 25 cases with a range of 30–100% positivity in the tumor cells." (PMID 30610490, 2019). "Noteworthy, the staining pattern of TWIST1 and NAT1 have appeared to be related to the EMT status of the primary tumor." (PMID 30610490, 2019). "In both HT-29 cells and MDA-MB-231 cells, a decrease in NAT1 expression significantly inhibits tumor growth in mice." (PMID 29518119, 2018). "A similar significant correlation was seen between NAT1 mRNA and tumor size, with an equally weak relationship (r = − 0.07, p = 0.0016)." (PMID 29969986, 2018). "Its potential target, arylamine N-acetyltransferase 1, is correlated with increased survival in patients with these tumor subtypes." (PMID 28970833, 2017). "Univariate analysis revealed significant associations between levels of expression of ERα (P = 0.0393), the levels of expression of NAT1 (P = 0.0005), tumor size (P = 0.0028), number of positive lymph nodes (P = 0.0006) and DFS." (PMID 25528056, 2014).
tumor (continued). "Univariate analysis indicated significant associations between levels of ERα (P = 0.0034), PgR (P = 0.0221), NAT1 (P = 0.0054), tumor size (P = 0.0188), number of positive lymph nodes (P = 0.0048) and OS." (PMID 25528056, 2014). "Levels of expression of NAT1 were positively correlated with those of ERα (P < 0.0001) and PgR (P < 0.0001), but negatively correlated with both tumor grade and size (P < 0.0001)." (PMID 25528056, 2014). "We showed that levels of expression of NAT1 were positively correlated with ERα and PgR, but negatively correlated with tumor grade and size." (PMID 25528056, 2014). "Levels of NAT1 were positively correlated with ERα (P < 0.0001) and PgR (P < 0.0001), but negatively correlated with tumor grade and size (P < 0.0001)." (PMID 25528056, 2014). "NAT1 samples (i.e., < 1 cm from the tumor) showed significantly elevated methylation levels (p <0.0001) in the epithelial cells in two of the three tumors, a finding that supports the concept of a field effect in CRC." (PMID 23988185, 2013). "NAT1 knock-down significantly slowed tumor formation in vivo, although the effect was only marginal." (PMID 21347396, 2011). "In addition, overexpression of NAT1 in combination with antiangiopoietin (bevacizumab) was more effective in preventing tumor metastasis in animal studies." (PMID 38916406, 2024). "Almost all patients who survived less than 2 years had tumours with no detectable NAT1 mRNA, suggesting NAT1 deficiency is a strong predictor of poor drug response." (PMID 35918499, 2022). "The class-independent effect of NAT1 deficiency may explain the poor response to chemotherapy seen in those patients with low tumour NAT1 expression." (PMID 35918499, 2022). "Moreover, gene expression in patient tumor samples showed a significant inverse relationship between NAT1 expression and MMP9 expression." (PMID 31910058, 2020). "In this study, we found that NAT1 mRNA expression was associated with tumor T stage, N stage, and clinical stage, but not M stage." (PMID 31781164, 2019). "Nevertheless, the growth of the NAT1 knock-down cells was attenuated, indicating that NAT1 may have a role in tumor cell growth and/or survival in vivo." (PMID 21347396, 2011). "This difference between the in vitro and in vivo NAT1 activities could be due to the presence of mouse cell infiltrates in the tumor samples, which express arylamine N-acetyltransferase." (PMID 21347396, 2011). "Moreover, its expression was significantly correlated with tumor grading and inversely correlated with the expression of its putative targets, N-acetyltransferase-1 (NAT1) and forkhead box A1 (FOXA1), the presence of which is specific for better outcomes for patients with luminal tumors." (PMID 35163157, 2022). "Compared to the immune infiltrate levels of six cells, deletion of NAT1 and NAT2 was associated with substantially lower levels of four immune cell types, including B cells, CD8+ T cells, neutrophils, and dendritic cells, which indicated their influence on the tumor microenvironment." (PMID 34322151, 2021). "NAT1 activity in the host also may be important for tumor progression." (PMID 29518119, 2018). "Firstly, NAT1 overexpression inhibits the occurrence and progression of epithelial-mesenchymal transition (EMT) in tumor cells." (PMID 38916406, 2024). "Arylamine N-acetyltransferase 1 (NAT1) was shown to catalyze the N- or O-acetylation of different arylamine and heterocyclic amine substrates and was observed to be involved in tumor progression and chemotherapy resistance." (PMID 37350934, 2023). "We applied Western blot to examine the expression of XBP1 and NAT1 in GBC and matched adjacent non-tumor tissues." (PMID 32793479, 2020). "NAT1: High expression of NAT1 is found in tumor tissues (CAB017782), while it is not detected in normal tissues, pointing towards its significance in tumor metabolism and survival." (PMID 40104502, 2025).